PDS5B (PDS5 cohesin associated factor B)
Description:
Regulator of sister chromatid cohesion in mitosis which may stabilize cohesin complex association with chromatin. May couple sister chromatid cohesion during mitosis to DNA replication. Cohesion ensures that chromosome partitioning is accurate in both meiotic and mitotic cells and plays an important role in DNA repair. Plays a role in androgen-induced proliferative arrest in prostate cells.
Synonyms: APRIN; AS3; KIAA0979; FLJ23236; CG008
Tractability: PROTAC: ubiquitination databases record sites on it; its protein half-life has been measured.
Gene: Protein-coding gene on chromosome 13 (32,586,315 to 32,778,022, forward strand). Ensembl gene ENSG00000083642.
Subcellular location: Nucleus
Subcellular location (Human Protein Atlas): Nucleoplasm
Pathways (Reactome):
Cell Cycle: Cohesin Loading onto Chromatin; Establishment of Sister Chromatid Cohesion; Resolution of Sister Chromatid Cohesion; Separation of Sister Chromatids
Gene Ontology:
Molecular function: DNA binding; protein binding; cohesin unloader activity
Biological process: mitotic sister chromatid cohesion; negative regulation of cell population proliferation; regulation of cell population proliferation; cell population proliferation; double-strand break repair via homologous recombination
Cellular component: chromatin; nucleoplasm; chromosome; chromosome, centromeric region; cytosol; nucleus; Shu complex
Genetic constraint (gnomAD): Loss-of-function variants: 17 observed, 51.23 expected, observed/expected ratio (o/e) 0.33, 90% interval 0.23 to 0.5. The upper end of that interval is the gene's LOEUF score, 0.5, which puts it in group 2 of 6, group 1 being the genes least tolerant of losing a copy. Missense variants: 440 observed, 597.79 expected, observed/expected ratio (o/e) 0.74, 90% interval 0.68 to 0.8. Synonymous variants: 201 observed, 207.83 expected, observed/expected ratio (o/e) 0.97, 90% interval 0.86 to 1.09.
Homologues: Orthologues: chimpanzee PDS5B (100% identical), macaque PDS5B (99% identical), dog PDS5B (99% identical), pig PDS5B (97% identical), mouse Pds5b (96% identical), rabbit PDS5B (96% identical), rat Pds5b (95% identical), guinea pig PDS5B (94% identical), tropical clawed frog pds5b (85% identical), zebrafish pds5b (80% identical), Drosophila melanogaster pds5 (31% identical), Caenorhabditis elegans evl-14 (20% identical). Paralogues in human: PDS5A (63% identical).
Diseases named in the same sentence as PDS5B in open-access papers:
PDS5B is named in the same sentence as 84 diseases in open-access papers, as found by Europe PMC text mining. Sharing a sentence is not in itself a finding about the gene and the disease. The quoted sentences say what the papers report.
breast carcinoma (40 papers, 2018 to 2025). "PDS5B codes for a protein required for pairing of sister chromatids during cell division, and down-regulation of PDS5B has been associated with breast cancer." (PMID 37026480, 2023). "Moreover, low Pds5B expression levels predict better survival in patients with breast and ovarian cancer, as the loss of Pds5B sensitizes breast cancer cells to DNA-damaging chemotherapy." (PMID 32760717, 2020). "PDS5B expression levels were reported to be associated with histological grade in breast cancer." (PMID 30776580, 2019). "In addition, a frameshift mutation of PDS5B is observed in breast cancer tissues and lymph nodes." (PMID 34226509, 2021). "It has been shown that PDS5B protein behaves as a tumour suppressor, as PDS5B gene expression level is reduced in gastric and colorectal cancers, and about 47% of breast cancer have low expression of PDS5B." (PMID 35509102, 2022). "It is also reported that nPD-L1 competes with WAPL for binding to PDS5B, and regulates breast cancer cell sister chromatid cohesion." (PMID 33139930, 2021). "Increased sensitivity to olaparib was also demonstrated with PDS5B (APRIN) depletion in breast cancer cells and in a zebrafish xenograft model." (PMID 34202641, 2021). "One study revealed that PDS5B expression is correlated with histological grade in breast cancer and the treatment efficacy of chemotherapy in breast cancer patients." (PMID 34226509, 2021). "PDS5B, as a BRCA2-interacting protein, is required for DNA repair and genome integrity in breast cancer cells." (PMID 34226509, 2021).
gastric cancer (22 papers, 2018 to 2025). A primary or metastatic malignant neoplasm involving the stomach. "PDS5B exhibits frameshift mutations in gastric cancer and colorectal cancer patients, which is associated with weak or negative PDS5B immunostaining." (PMID 34226509, 2021).
colorectal cancer (14 papers, 2018 to 2024). A primary or metastatic malignant neoplasm that affects the colon or rectum. "Additionally, loss of PDS5B was found to be a feature of gastric and colorectal cancers with high microsatellite instability." (PMID 30776580, 2019).
ovarian carcinoma (13 papers, 2019 to 2024). A malignant neoplasm originating from the surface ovarian epithelium. "For instance, low expression of PDS5B is associated with better survival in patients with ovarian cancer." (PMID 34226509, 2021). "As a result, low expression of PDS5B levels is correlated with better survival in patients with breast and ovarian cancer." (PMID 34070827, 2021). "The correlation between low expression of PDS5B levels and better survival rates is also found in patients with ovarian cancer." (PMID 34070827, 2021). "Downregulation of PDS5B increased the sensitivity of the PARP inhibitor Olaparib, indicating that PDS5B is a potential target for treating ovarian cancer." (PMID 34226509, 2021).
prostate carcinoma (13 papers, 2009 to 2025). A carcinoma that arises from epithelial cells of the prostate gland. "Hence, the miR-223/PDS5B complex plays a critical role in the regulation of cell proliferation and invasion in prostate cancer cells." (PMID 35205115, 2022). "Furthermore, overexpression of PDS5B, which acts as a tumor suppressor gene, leads to the reversal of mR-223-mediated tumor progression in prostate cancer cells." (PMID 35205115, 2022).
acute myeloid leukemia (10 papers, 2019 to 2024). Acute myeloid leukemia (AML) is a group of neoplasms arising from precursor cells committed to the myeloid cell-line differentiation. "Mutations in the cohesin complex components (STAG2, RAD21, SMC1A, SMC3, and PDS5B) are recurrent genetic drivers in myelodysplastic neoplasm (MDS) and acute myeloid leukemia (AML)." (PMID 39033241, 2024). "For example, somatic mutations in the eight genes that comprise the cohesin ring (SMC1A, SMC3, STAG1, STAG2, RAD21) and the cohesin-ring support genes (NIPBL, MAU2, WAPL, PDS5A, PDS5B) and CTCF are frequently found in many cancer types and are especially common in acute myeloid leukemia (AML)." (PMID 36171609, 2022).
pancreatic cancer (7 papers, 2019 to 2024). "miR-223 causes the reduction of PDS5B protein levels and promotes the growth of pancreatic cancer cells, whereas increase of PDS5B by overexpressing PDS5B or miRNA-223 inhibitor inhibits cancer cell growth." (PMID 34070827, 2021). "The association of reduced expression of PDS5B with increase of survival rates is also observed in patients with pancreatic cancer." (PMID 34070827, 2021). "It has been reported that miR-223 promotes the viability and motility of pancreatic cancer cells via inhibition of PDS5B in pancreatic cancer cells." (PMID 34226509, 2021). "PDS5B alleviates cell viability, migration, and invasion via promoting Ptch2 expression in pancreatic cancer cells." (PMID 34226509, 2021). "Overexpression of PDS5B represses cell viability and stimulates apoptosis in pancreatic cancer cells, while depletion of PDS5B increases migratory and invasive ability." (PMID 34226509, 2021). "In pancreatic cancer cells, miR‐223 promotes cancer cell proliferation and invasion by targeting PDS5B which acts as a repressor of pancreatic cancer development." (PMID 32491253, 2020). "One study revealed that PDS5B exerts antitumor activity in pancreatic cancer cells." (PMID 34226509, 2021). "In addition, miRNA-223 microRNA could interact with PDS5B mRNA, and inducing PDS5B expression or using miRNA-223 inhibitor could inhibit pancreatic cancer cell growth." (PMID 35509102, 2022).
lung carcinoma (6 papers, 2019 to 2025). "In line with this concept, PDS5B was associated with the expression of LATS1 in tumor tissues of lung cancer patients." (PMID 34226509, 2021). "Strikingly, low expression of PDS5B was associated with lymph node metastasis in lung cancer patients." (PMID 34226509, 2021). "Moreover, low expression of PDS5B was associated with lymph node metastasis in lung cancer patients." (PMID 34226509, 2021). "Therefore, in this study, we explored the biological functions of PDS5B in lung cancer cells and determined its underlying molecular mechanism." (PMID 34226509, 2021). "In the current study, low expression of PDS5B was observed and correlated with lymph node metastasis in lung cancer patients, indicating that PDS5B might be associated with the prognosis of lung cancer patients." (PMID 34226509, 2021). "In support of the tumor-suppressive role of PDS5B, our present study demonstrated that PDS5B upregulation repressed viability, migration, and invasion of lung cancer cells, while PDS5B knockdown promoted viability and motility of NSCLC cells." (PMID 34226509, 2021). "In the present study, we reported that PDS5B positively regulated the expression of LATS1 in lung cancer cells." (PMID 34226509, 2021). "Strikingly, PDS5B upregulation retarded tumor growth in vivo, further supporting the anticancer role of PDS5B in lung cancer." (PMID 34226509, 2021). "The expression levels of PDS5B in the panel of lung cancer cells and the normal lung epithelial BEAS-2B cells were measured by western blotting." (PMID 34226509, 2021). "To determine whether PDS5B could retard tumor growth in vivo, we performed a mouse study using lung cancer xenografts in nude mice." (PMID 34226509, 2021). "Notably, the expression of PDS5B was correlated with LATS1 expression levels in tumor specimens in lung cancer patients." (PMID 34226509, 2021). "Furthermore, we detected the expression of PDS5B in tissue samples of lung cancer patients by immunohistochemical study." (PMID 34226509, 2021). "It is required to investigate whether miR-223 or other miRNAs target PDS5B expression in lung cancer cells, which will help us understand the regulatory mechanism of PDS5B." (PMID 34226509, 2021). "To ascertain the expression of PDS5B in tumor specimens of lung cancer patients, we used immunohistochemical staining to detect PDS5B expression levels in tumor tissues of 232 patients with lung cancer." (PMID 34226509, 2021). "It is necessary to determine whether upregulation of PDS5B could enhance the sensitivity of chemotherapeutic drugs in lung cancer." (PMID 34226509, 2021). "However, the biological functions of PDS5B in lung cancer and its underlying mechanisms are not fully elucidated." (PMID 34226509, 2021). "Our findings suggest that PDS5B might be a therapeutic target for lung cancer." (PMID 34226509, 2021). "Notably, overexpression of LATS1 abrogated PDS5B knockdown-induced tumor promotion in NSCLC cells, suggesting that LATS1 is involved in PDS5B-mediated anticancer activity in lung cancer." (PMID 34226509, 2021). "The functions and role of PDS5B in lung cancer cells have not been fully elucidated." (PMID 34226509, 2021).
oral squamous cell carcinoma (6 papers, 2019 to 2024). "Interestingly, PDS5B was highly expressed in oral squamous cell carcinoma, suggesting that the function of PDS5B could be cell-type dependent." (PMID 30776580, 2019).
cervical carcinoma (5 papers, 2015 to 2025). A carcinoma arising from either the exocervical squamous epithelium or the endocervical glandular epithelium. "First, we sought to determine the expression levels of the Pds5A and Pds5B proteins and their intracellular localization at specific stages of the cell cycle in a synchronized population of human cervical carcinoma cells (HeLa)." (PMID 32760717, 2020). "PDCD6 gene expression was higher in cells sensitive to L-OHP, whileexpression of PDS5B, UBL3, MTIF3,XPO4, CASC8, and GTF3A was lower.UBL3 was identified as one of seven genes that predict relapse andsurvival in early-stage cervical carcinoma patients." (PMID 26678268, 2015).
asthma (4 papers, 2020 to 2023). "Interestingly, five of these loci, i.e., ACTN1, PDS5B, SEMA6D, SPRY4, and TENM3, have been reported of association with the genetic susceptibility of asthma." (PMID 36051697, 2022).
breast tumors (1 paper, 2021). "Immunohistochemistry analysis indicates that nearly 47% of breast tumors tested had reduced expression of PDS5B and the frequency of low PDS5B expression is significantly correlated with histological grade (i.e., the higher the grade of cancers, the lower the expression of PDS5B)." (PMID 34070827, 2021).
Cerebral ischemia (1 paper, 2025). Restriction of arterial blood supply to the brain associated with insufficient oxygenation to support the metabolic requirements of the tissue. "In patients after cerebral ischemia, a significant increase in the expression of circRNA PDS5B in lymphocytes and granulocytes and only in granulocytes for circRNA CDC14A was found, and their levels positively correlated with the infarct volume." (PMID 41245147, 2025). "Moreover, it was revealed that the concentrations of circRNA FUNDC1, circRNA PDS5B and circRNA CDC14A in blood were significantly increased in patients after cerebral ischemia, and their levels correlated with the infarct size." (PMID 41245147, 2025).
diaphragmatic hernia (1 paper, 2009). A congenital or acquired weakness or opening in the diaphragm which allows abdominal contents to protrude into the chest cavity; congenital diaphragmatic hernias are caused when the embryonic diaphragm fails to fuse. "Similar to human CdLS, Pds5B mutant mice exhibit variable expressivity of phenotypes, but unlike human CdLS, Pds5B mutant mice do not have diaphragmatic hernia or eye or kidney abnormalities, which are associated with CdLS." (PMID 19412548, 2009).
diffuse large B-cell lymphoma (1 paper, 2019). "Similar to CHD1, PDS5B deletion was detected in 50% of the cancer types; the highest deletion frequencies were in PCA, sarcoma and diffuse large B-cell lymphoma." (PMID 31222142, 2019).
embryonal carcinoma (1 paper, 2019). A non-seminomatous malignant germ cell tumor characterized by the presence of large germ cells with abundant cytoplasm resembling epithelial cells, geographic necrosis, high mitotic activity, and pseudoglandular and pseudopapillary structures formation. "Notably, loss of PDS5B disrupted stem cell programs in embryonal carcinoma as a new mechanism of PDS5B in tumor suppression." (PMID 30776580, 2019).
esophageal squamous cell carcinoma (1 paper, 2020). Esophageal squamous cell carcinoma (ESCC) is a type of esophageal carcinoma (EC) that can affect any part of the esophagus, but is usually located in the upper or middle third. "Two genes, DEFB4A and PDS5B, are associated (GeneRIF) with Esophageal squamous cell carcinoma (ESCC)." (PMID 32586322, 2020).
gastrointestinal stromal tumor (1 paper, 2019). "Similarly, low PDS5B was correlated with longer overall survival of gastrointestinal stromal tumors." (PMID 30776580, 2019).
heart defects (1 paper, 2009). "Indeed, we found that Pds5A−/− mice, compared to wildtype mice, had significantly higher incidence of congenital heart defects (17/25 versus 3/18, P<0.001), including those that are commonly found in CdLS patients and Pds5B-deficient mice." (PMID 19412548, 2009).
heart failure (1 paper, 2009). Inability of the heart to pump blood at an adequate rate to meet tissue metabolic requirements. "While Pds5A−/− and Pds5B−/− mice die at birth, embryos harboring 3 mutant Pds5 alleles die between E11.5 and E12.5 most likely of heart failure, indicating that total Pds5 gene dosage is critical for normal development." (PMID 19412548, 2009).
Hirschsprung disease (1 paper, 2009). Hirschsprung disease (HSCR) is a congenital intestinal motility disorder that is characterized by signs of intestinal obstruction due to the presence of an aganglionic segment of variable extent in the terminal part of the colon. "Indeed, the identification of PDS5B mutations in a family with CdLS and megacolon suggests that PDS5B could be a modifier for Hirschsprung disease and, that these two disorders may share additional molecular pathways." (PMID 19412548, 2009).
Infertility (1 paper, 2019). "Several CDK2-bound genes have also been implicated in other aspects of germ cell development, including Palb2, Pds5b, Safb1, and Herc4, or have been investigated as potential markers of infertility in human populations: Mtrr and Vdac3." (PMID 31350280, 2019).
megacolon (1 paper, 2009). "In summary, we have discovered that PDS5B is mutated in a familial case of CdLS with megacolon, and that PDS5A and PDS5B have both redundant and distinct roles in development that are likely unrelated to its ancient function in sister chromatid cohesion." (PMID 19412548, 2009). "This family therefore represents a familial CdLS case with atypical inheritance that includes associations with megacolon and mutation of the PDS5B gene." (PMID 19412548, 2009). "We further identified a functional missense mutation (R1292Q) in the PDS5B DNA-binding domain in a familial case of CdLS, in which affected individuals also develop megacolon." (PMID 19412548, 2009).
ptosis (1 paper, 2009). The drooping of the upper eyelid. "The defects in sympathetic innervation emanating from the superior cervical ganglion (SCG) observed in Pds5B-deficient mice could explain the ptosis frequently associated with CdLS." (PMID 19412548, 2009).